PTMA (prothymosin alpha)
Description:
Prothymosin alpha may mediate immune function by conferring resistance to certain opportunistic infections.
Synonyms: TMSA
Tractability: PROTAC: UniProt records ubiquitination sites on it; ubiquitination databases record sites on it; its protein half-life has been measured.
Gene: Protein-coding gene on chromosome 2 (231,706,895 to 231,713,552, forward strand). Ensembl gene ENSG00000187514.
Subcellular location: Nucleus
Subcellular location (Human Protein Atlas): Nucleoplasm; Cytosol
Gene Ontology:
Molecular function: calcium ion binding; DNA-binding transcription factor binding; histone binding; protein binding; histone chaperone activity
Biological process: negative regulation of apoptotic process; DNA-templated transcription; positive regulation of transcription by RNA polymerase II; chromatin organization
Cellular component: cytosol; nucleoplasm; nucleus
Genetic constraint (gnomAD): Loss-of-function variants: 4 observed, 16.51 expected, observed/expected ratio (o/e) 0.24, 90% interval 0.12 to 0.55. The synonymous counts are far from expectation, so gnomAD's model fits this gene poorly and the ratio says little. Missense variants: 120 observed, 127.1 expected, observed/expected ratio (o/e) 0.94, 90% interval 0.81 to 1.1. Synonymous variants: 58 observed, 42.51 expected, observed/expected ratio (o/e) 1.36, 90% interval 1.1 to 1.7.
Homologues: Orthologues: macaque PTMA (100% identical), mouse Ptma (96% identical), pig PTMA (86% identical), zebrafish si:ch211-222l21.1 (57% identical).
Diseases named in the same sentence as PTMA in open-access papers:
PTMA is named in the same sentence as 51 diseases in open-access papers, as found by Europe PMC text mining. Sharing a sentence is not in itself a finding about the gene and the disease. The quoted sentences say what the papers report.
COVID-19 (10 papers, 2020 to 2024). A disease caused by infection with severe acute respiratory syndrome coronavirus 2. "PTMA may protect T-cells during lymphopenia in COVID-19 and the administration of thymosin alpha- 1(Tα1), final product of PTMA, is suggested as a potential approach to protect effector T-cells during COVID-19." (PMID 36142365, 2022).
breast carcinoma (8 papers, 2000 to 2025). "We note significant upregulation of genes such as EFNA1, PTMA, SPINT2, and CD24, which have previously been indicated in increased tumor aggression and driving the transition to invasive forms of breast cancer." (PMID 39801521, 2025).
colorectal cancer (6 papers, 2020 to 2024). A primary or metastatic malignant neoplasm that affects the colon or rectum. "As a target gene of miR-370-5p in this work, PTMA, a nuclear protein, has been reported to be activated in esophageal cancer, colorectal cancer, and glioma." (PMID 38619648, 2024). "Hsa_circ_0004277 promotes the proliferation of colorectal cancer cells, acting as a miR-512-5p sponge to upregulate the expression of an oncogene PTMA (Prothymosin alpha) in CRC." (PMID 34298612, 2021). "Prothymosin-α (PTMA), showing increased levels in patients treated with 5-fluorouracil, is associated with a negative prognosis in colorectal cancer." (PMID 39494346, 2024).
glioma (4 papers, 2021 to 2024). A benign or malignant brain and spinal cord tumor that arises from glial cells (astrocytes, oligodendrocytes, ependymal cells). "The release of prothymosin alpha (ProTα)-EGFP from C6 glioma cells was significantly inhibited by treatment with ethylene glycol tetraacetic acid (EGTA)." (PMID 33807671, 2021). "Prothymosin alpha (ProTα) and S100A13 are released from C6 glioma cells under serum-free conditions via membrane tethering mediated by Ca2+-dependent interactions between S100A13 and p40 synaptotagmin-1 (Syt-1), which is further associated with plasma membrane syntaxin-1 (Stx-1)." (PMID 33807671, 2021).
non-small cell lung carcinoma (4 papers, 2019 to 2023). A group of at least three distinct histological types of lung cancer, including non-small cell squamous cell carcinoma, adenocarcinoma, and large cell carcinoma. "In the case of prothymosin alpha (PTMA) protein, in which overexpression indicates a poor prognosis for most cancers, its inhibition described in non-small cell lung cancer allows cells to be sensitised to radiation therapy." (PMID 37377864, 2023). "In non-small cell lung cancer, lncRNA CYTOR upregulated radioresistance via miR-206/PTMA axis, and PTMA (prothymosin alpha) involved in inhibiting apoptosis." (PMID 35600868, 2022). "It regulates prothymosin-α (PTMA) and purine nucleoside phosphorylase (PNP) in bladder cancer and PIK3CA in NSCLC (Non-small cell lung carcinoma)." (PMID 30862091, 2019).
bladder cancer (3 papers, 2019 to 2025). "PTMA was identified as a target gene regulated by the miR-1 in bladder cancer." (PMID 36873948, 2023).
hepatocellular carcinoma (2 papers, 2015 to 2024). A malignant tumor that arises from hepatocytes. "Kinase inhibitor sorafenib impairs prothymosin alpha PTMA expression in hepatocellular carcinoma (HCC)." (PMID 38731835, 2024).
Opportunistic infection (2 papers, 2016 to 2021). An infection that is caused by a pathogen that would generally not be able to cause an infection in a host with a normal immune system. "Prothymosin, Alpha (PTMA) works as a mediator for immune function by conferring resistance to certain opportunistic infections like Candidiasis and Kaposi’s Sarcoma." (PMID 27050411, 2016). "PTMS-encoded parathymosin may mediate immune function by blocking the effects of prothymosin-alpha that confers resistance to certain opportunistic infections." (PMID 34646294, 2021).
Anxiety (1 paper, 2019). Intense feelings of nervousness, tension, or panic often arise in response to interpersonal stresses. "Prothymosin alpha has been reported to influence locomotor activity, memory-learning, and anxiety behavior in mice, as well as modulating linker histone interaction to promote transcription." (PMID 31783652, 2019).
cystic fibrosis-related diabetes (1 paper, 2023). Cystic fibrosis-related diabetes is a form of diabetes that occurs frequently in individuals with cystic fibrosis. "Additional genes implicated in the development of cystic fibrosis-related diabetes (CFRD) include PM20d1, which is located near the SLC26A9 gene, and PTMA." (PMID 37893045, 2023).
gastric cancer (1 paper, 2024). A primary or metastatic malignant neoplasm involving the stomach. "The PTMA gene, one of the 12 identified prognostic markers, exhibited significant overexpression in gastric cancer tissues compared to normal tissues." (PMID 39478860, 2024). "This suggests that PTMA knockdown promotes apoptosis in gastric cancer cells." (PMID 39478860, 2024).
ischemia (1 paper, 2019). A hypoperfusion of the BLOOD through an organ or tissue caused by a PATHOLOGIC CONSTRICTION or obstruction of its BLOOD VESSELS, or an absence of BLOOD CIRCULATION. "P6Q is a minimised biologically active peptide derived from prothymosin alpha (ProTα), a nuclear protein implicated in the inhibition of ischemia-induced necrosis and apoptosis in the brain and retina." (PMID 30814559, 2019).
myocardial diseases (1 paper, 2024). "The overexpression of PTMA in cardiomyocytes stimulated their proliferation through the increased expression of the cell cycle genes and improved cardiac regeneration; thus, it is a relevant gene for the treatment of myocardial diseases." (PMID 38380430, 2024).
neuroblastoma (1 paper, 2008). Neuroblastoma (NB) is the most common solid, extracranial childhood tumor. "Because increased activity of MYCN in stage 4s-NA or c-MYC in stage 4-NA tumors should both result in high expression of shared target genes compared to localized-NA neuroblastomas, we analyzed known direct MYCN/c-MYC target genes, namely MDM2, DKC1, and PTMA, in neuroblastoma subtypes." (PMID 18851746, 2008).
oral cancer (1 paper, 2022). "A study involving a proteomics-based approach identified numerous protein markers, namely prothymosin alpha (PTMA), S100A7, 14-3-3ζ, 14-3-3δ, hnRNPD, and hnRNPK, used for distinguishing between normal mucosa, dysplasia, and oral cancer." (PMID 35741145, 2022).
osteoporosis (1 paper, 2012). A condition of reduced bone mass, with decreased cortical thickness and a decrease in the number and size of the trabeculae of cancellous bone (but normal chemical composition), resulting in increased fracture incidence. "PTMA (prothymosin, alpha) may play important roles in osteoporosis." (PMID 22957024, 2012).
polycystic kidney disease (1 paper, 2006). A usually autosomal dominant and less frequently autosomal recessive genetic disorder characterized by the presence of numerous cysts in the kidneys leading to end-stage renal failure. "Prothymosin alpha is an oxidative stress-protecting gene and transgenic mice over-expressing this transcript develop polycystic kidney disease PKD." (PMID 16420690, 2006).
prostate carcinoma (1 paper, 2017). A carcinoma that arises from epithelial cells of the prostate gland. "Moreover, miR-1 represses genes such as PNP (purine nucleoside phosphorylase) and PTMA (prothymosin-α), leading to down-regulation of pathways regulating the cell cycle, mitosis, DNA replication, and actin dynamics in prostate cancer." (PMID 28537886, 2017).
pulpitis (1 paper, 2025). Inflammation of the dental pulp. "In rat pulpitis models, both prothymosin α (PTMA, precursor of thymosin α1) gelatin sponge placed at the hole of pulp (LPS-P(gs)) and PTMA injection in pulp (LPS-P(i)) significantly reduced infiltration of inflammatory cells and expression of PTGS2, and increased the expression of GPX4." (PMID 41087337, 2025).
thymoma (1 paper, 2016). A neoplasm arising from the epithelial cells of the thymus. "Downregulation of prothymosin alpha was observed in types A and B3 thymomas, with significant changes observed in B3, -1.68 (q-value 0.247) and -1.65 (q-value 0.0262) respectively." (PMID 27832160, 2016).
cancer (21 papers, 2011 to 2025). A tumor composed of atypical neoplastic, often pleomorphic cells that invade other tissues. "We then found that the most significant DEGs were tightly associated with progression of cancers, including PTMA, HNRNPR, RAPH1, TRAF3IP1, CNBP, and PRR15." (PMID 41347062, 2025). "Prothymosin-α (PTMA), a nuclear protein, is strikingly associated with unfavorable clinical outcomes in many cancers." (PMID 35297481, 2022). "Prothymosin α (PTMA) generates a great deal of interest among investigators due to its robust involvement in a variety of biological processes ranging from cell proliferation as observed in several types of cancer and apoptosis to its association with cell-mediated immunity." (PMID 26932824, 2016). "Interestingly, Ptma is a well-known gene encoding prothymosin alpha, which upon cleavage becomes thymosin alpha, a peptide that has been well studied in the context of immunity and that is used in the treatment of Hepatitis B and C and cancer." (PMID 26431182, 2015). "C-Myc has been shown to regulate the expression of the prothymosin alpha (PTMA) gene, which is responsible for cell proliferation in many types of cancer." (PMID 34440124, 2021). "Analysis of gene essentiality in 517 cancer cell lines (including 53 OC cell lines) show that PTMA, INTS1, and NOC2L are all common essential genes in cancer." (PMID 32332753, 2020). "PTMA (prothymosin, alpha isoform 2) is over-expressed in a number of different cancers and interacts with histone acetyltransferases." (PMID 21915259, 2011). "Prothymosin-α, an oncoprotein encoded by PTMA, was found overexpressed specifically in TNBC lymph nodes with cancer cells, which is consistent with the malignancy of cancer infiltration reported by other researchers." (PMID 34611125, 2021). "Several housekeeping genes, such as ACTB, TUBB1, and PTMA, as well as noncoding RNAs, such as srpRNA (RN7SL2), are highly abundant in the plasma of both cancer patients and HDs." (PMID 35816095, 2022). "Seven reference genes (YWHAZ, GNAS, GAPDH, OAZ1, PTMA, B2M, and ACTB) were screened out among the 95 candidate reference genes from the data set of the platelets’ transcriptome of pan-cancer and 73 commonly known reference genes." (PMID 35770000, 2022). "Another interesting gene would be PTMA, which shows significantly higher proportion of MAE cells in the relapsed sample, and studies demonstrated that, though in other types of cancers, it can predict recurrence and poor prognosis." (PMID 34722498, 2021). "Therefore PTMA siRNA may have potential applications as an adjuvant in cancer chemotherapy." (PMID 22059741, 2011). "GEL cohort data also provided support for PTMA (prothymosin alpha) as a putative driver gene, previously implicated in TGCT, though not currently included in the COSMIC Cancer Gene Census20,21." (PMID 39461959, 2024).
tumor (12 papers, 2013 to 2025). "However, thymosin α1 can be monitored through its uncleaved precursor prothymosin alpha found inside epithelial tumor cells." (PMID 27832160, 2016).
PTMA also shares sentences with these, for which no sentence is quoted: Sepsis (6 papers); colon cancer (3); diabetes (3); breast tumors (2); cardiovascular disease (2); lung carcinoma (2); lymphopenia (2); malignant ovarian tumors (2); nasopharyngeal carcinoma (2); acute pancreatitis (1); adenoma (1); candidiasis (1); depression (1); esophageal cancer (1); esophageal squamous cell carcinoma (1); gastrointestinal disease (1); HCMV infection (1); head and neck cancer (1); immune deficiency (1); immune dysfunction (1); infection (1); Kaposi's sarcoma (1); lymph node metastasis (1); oral submucous fibrosis (1); ovarian carcinoma (1); pancreatic adenocarcinoma (1); pulmonary tuberculosis (1); testicular cancer (1); type 2 diabetes mellitus (1).